CD28 (CD28 molecule)
Diseases named in the same sentence as CD28 in open-access papers (continued):
Sharing a sentence is not in itself a finding about the gene and the disease.
tumor (continued). "Axicabtagene contains a murine extracellular scFv of the FMC63 monoclonal antibody that binds to CD19 on tumor cells followed by a human CD28α hinge and transmembrane domain fused to the costimulatory molecule CD28 and the T cell activation domain CD3ζ chain." (PMID 40061940, 2025). "We analyzed CARIS membrane lipid rafts (mLRs) and found that, upon tumor engagement, CD28.ζ-CAR molecules rapidly but transiently translocated into mLRs, mobilizing the microtubular organizing center and lytic granules to the CARIS." (PMID 39792660, 2025). "For example, IL-15 provided a less differentiated phenotype, with higher CD27 and CD28 expression, improving in vivo persistence and anti-tumor immunity in tumor-bearing hosts." (PMID 41346587, 2025). "Given that checkpoint inhibitors function in part by restoring CD28 signaling, it is unsurprising that XmAb808 combined with an anti–PD-1 was more efficacious in a mouse xenograft tumor model than either agent alone." (PMID 39301613, 2025). "Chimeric antigen receptor T cells (CART) targeting CD19 through CD28.ζ signaling induce rapid lysis of leukemic blasts, contrasting with persistent tumor control exhibited by 4-1BB.ζ-CART." (PMID 39792660, 2025). "In the Nalm6 model, more mice in the NKG2D/CD28&CD19 CAR-T cell group achieved complete tumor clearance compared to the traditional CD19 CAR-T cell group." (PMID 40181405, 2025). "CAR-T-cells targeting the prostate-specific membrane antigen (PSMA) with CD28 co-stimulation have shown enhanced in-vivo anti-tumor effects, promising for CRPC treatment." (PMID 40260236, 2025). "Other studies have shown that PD-L1 expression on DCs from peripheral blood and tumor tissues can be ≥20 times higher than B7-1, and PD-L1 can bind B7.1 in cis, limiting B7.1’s interaction with T-cell CD28 and weakening T-cell activation." (PMID 40573908, 2025). "The co-expression of the NKG2D/CD28 CCR in CAR-T cells offers a dual-activation strategic advantage by enhancing the anti-tumor functions and maintaining a youthful phenotype." (PMID 40181405, 2025). "After that, the tumor tissue microarrays were subjected to multi-label immunofluorescence staining of CD28 (yellow), CD68 (green), CD80 (red), and CD8 (orange)." (PMID 40541951, 2025). "We investigated the correlation between the proportion of tumor-infiltrating CD28−/CD8+ T cells and various clinical characteristics, including stage, pathological grade, deep myometrial invasion, and LVSI." (PMID 40136325, 2025). "For instance, the co-immunostimulatory genes CD226 and CD28 are essential for T cell activation and enhancement of anti-tumor immune responses." (PMID 40723280, 2025). "We screened purified CD8+ T cells from healthy volunteers and co-cultured CD3/CD28-activated CD8+T cells with tumor cells." (PMID 40040705, 2025). "These CD4+ T cells were ex vivo expanded with the treatment of Δ35 mM NaCl, anti-CD3/CD28, IL-2 and IL-7 along with heat-killed tumor cells." (PMID 40563574, 2025). "Circulating CD8+CD38+ T cells, CD8+CD28+ T cells, and NK cells were identified as potential prognostic factors for tumor response and survival in patients with HCC." (PMID 38404585, 2024). "From a clinical perspective, we found that the levels of CD8+CD28+ T, NK, and CD8+CD38+ T cells were associated with tumor characteristics and liver function, which, to some extent, would explain their prognostic value." (PMID 38404585, 2024). "The role of tumor‐secreted galectin‐9 in CD8+ T cell exhaustion was further validated using PBMC activated by CD3/CD28 and conditioned medium collected from galectin‐9‐manipulated cell lines." (PMID 38528665, 2024). "Although, these independent prognostic factors were associated with progressive tumor characteristics (p<0.05), with the exception of CD8+CD28+ T cells, changes in these factors before and after treatment were unassociated with tumor response (p > 0.05)." (PMID 38404585, 2024).
tumor (continued). "Using costimulatory molecules like CD28 or CD137 alongside a tumor antigen instead of CD3, specifically targeting a subset of antigen-experienced T cells, reduces toxicity." (PMID 38785789, 2024). "High-throughput genetic screening of T cells is conducted through TCR stimulation with anti-CD3/CD28 and IL-2, co-culturing with tumor cells (in vitro), or implantation in tumor-bearing mice (in vivo)." (PMID 39538305, 2024). "In contrast, immunostimulators like CD28 enhance T-cell activation and proliferation, promoting anti-tumor immune responses." (PMID 38300311, 2024). "This condition mimics T-cell activation via the TCR/CD3 complex and CD28 costimulation, which occurs via dialog between an antigen-specific T-cell and an activated, antigen-presenting DC in either the lymph node or the tumor." (PMID 38383773, 2024). "The topical application of anti-FAP CAR-T cells, combined with CD28, ΔCD28, 4-1BB co-stimulatory domains and PD-1 inhibition has been shown to provide transient tumour control and improve the survival in humanized mouse MM models." (PMID 38475858, 2024). "4-1BB-based CARs induce lower expression of exhaustion markers, more central memory T cell polarization and slower, but more persistent, tumor eradication than CD28-based CARs25,26." (PMID 38307904, 2024). "Recent reports have suggested that the CD28/CD86 axis in a tumor context is necessary to prevent final CD8 T cell exhaustion and its accumulation.." (PMID 38812523, 2024). "To investigate, we first evaluated T cell proliferation using cocultures of CFSE‐stained, CD3/CD28‐stimulated autologous PBMCs and tumor or normal lung organoids, respectively." (PMID 38528665, 2024). "Replacing the 4-1BB with a CD28 CSD resulted in a more rapid tumor eradication but at a price of decreased persistence and increased exhaustion for CAR T-cells as suggested by other studies." (PMID 39043633, 2024). "Direct CD28 stimulation of TILs does, however, did show potential in vitro, reinvigorating anti-tumour CD8 TIL function and metabolic activity." (PMID 38440738, 2024). "Inclusion of a 4-1BB intracellular co-stimulatory signal domain provided better tumor killing than did a PSCA-CAR containing a CD28 co-stimulatory signal domain." (PMID 38789450, 2024). "High-throughput genetic screening can discern persistence factors by repeatedly stimulating T cells with anti-CD3/CD28 and IL-2 in vitro, or by implanting them into tumor-bearing mice and comparing chronically stimulated T cells with unstimulated counterparts." (PMID 39538305, 2024). "The second-generation CAR-T cells have enhanced tumor suppression ability and persistence given the addition of CD28 or 4-1BB co-stimulatory molecules." (PMID 39735536, 2024). "Higher CD28 expression in primary tumor tissues suggests inhibition of T-lymphocyte activity and correlates with an earlier TNM stage and fewer metastatic lymph nodes." (PMID 39684559, 2024). "A tumor-specific CD28+ γδ T cell subset with potential antitumor activity is identified, emphasizing its role in preventing tumor recurrence in LT recipients." (PMID 38338658, 2024). "One construct with the costimulatory domain CD28 demonstrated the efficient inhibition of U87MG glioblastoma tumor cell growth in a xenograft tumor mouse model." (PMID 39769267, 2024). "Unlike FPT155, ALPN-202 is a mutated CD80-Fc fusion protein designed to overcome checkpoint inhibitor resistance by enhancing CD28 costimulation in the tumor microenvironment while inhibiting PD-L1 and CTLA-4." (PMID 39575257, 2024). "In this study, the incorporation of the 4-1BB endodomain at the distal position to the cell membrane resulted in a reduction of the anti-tumor effect induced by CAR containing only the CD28 costimulatory domain." (PMID 38455066, 2024).
tumor (continued). "Tregs, as one of the most important parts of immunosuppressive cells, can inhibit tumor-specific immune responses with the co-inhibitory molecules such as CTLA-4, TIGIT, LAG3, and CD28, and promote immune evasion, thus facilitating tumor cell proliferation." (PMID 38671348, 2024). "The second- and third-generation CAR-T cells incorporate 4–1BB or CD28 co-stimulatory molecules together with CD3ζ, significantly enhancing the anti-tumor effects of the cells, as well as the persistence and proliferation of the CAR-Ts in vivo." (PMID 38919533, 2024). "We generated tumor-educated, antigen-specific T cells and compared the effector T cell functionality effects on PDAC cells between tumor-educated and anti-Cd3e/Cd28-activated T cells." (PMID 38654067, 2024). "Recent studies have shown that inadequate activity of the costimulatory molecule CD28 on T cells can lead to a decrease in the anti-tumor activity of T cells." (PMID 39575257, 2024). "CD28-activated T cells had a strong transient mortality, while 4-1BB-activated T cells had better anti-tumor persistence." (PMID 38789450, 2024). "When CTLA4-mediated interactions with squamous cell carcinoma cells were blocked in vitro, tumor-CD80 engaged instead with CD28 on activated T cells." (PMID 39575257, 2024). "To further understand the pro-inflammatory impact of GzB-IL18, we co-cultured pCAR-H/T T cells and their armored derivatives with MDA-MB-468 tumor cells or anti-CD3+CD28 beads and measured tumor necrosis factor (TNF)-⍺ and IL2 in derived supernatants." (PMID 38745414, 2024). "As CD28 has been described to be expressed constitutively on naive T cells, agonistic targeting of CD28 is hard to restrict to the TIME or to circulating tumour-specific T cells." (PMID 38440738, 2024). "This is especially true for CD28 based CARs which have been shown to elicit a robust acute anti-tumor response because of stronger signaling strength and faster kinetics." (PMID 39885989, 2024). "The CD28 total cell LI showed significantly higher expression within the invasive front (p = 0.005) and the tumor core of cSCC cases (p < 0.001) as compared to BCC cases." (PMID 39329753, 2024). "Similar to CD80, CD86 is also a co-stimulatory molecule that enhances T cell activation and proliferation by binding to CD28 on T cells, aiding in the anti-tumor immune response." (PMID 39290697, 2024). "The combination of the B7 molecule and CD28-activated Th1 and Th2 cells induced the proliferation and activation of Th1 cells, promoted the recovery of immune function, and activated anti-tumor immune response by Th1 cytokines." (PMID 38415245, 2024). "Confocal immunofluorescence analysis revealed a positive quantitative correlation between pTCD8+CD28- and infiltrated CD8 + CD28- T cells in the paired tumour lesions (P = 0.037, right)." (PMID 38519706, 2024). "Recent studies have demonstrated the importance of CD28 in glycolysis as well as in antitumor effector differentiation and function within the tumor microenvironment." (PMID 38233562, 2024). "Several risk factors for CRS have been identified, including high CAR-T cell doses, CD28 as a costimulatory domain, high tumor burden and a low CD4/CD8 ratio in the infusion product." (PMID 39594822, 2024). "In another co-culture system, tumor organoids are incubated with peripheral blood mononuclear cells (PBMCs), which are stimulated with tumor organoids dissociated into single cells or with anti-CD3/anti-CD28." (PMID 38258518, 2024). "Accordingly, the presence of VM can affect the infiltration of immune cells into the tumour through the upregulation of immune checkpoints, such as CD28, CD86, BLTA, and CD40LG, which can inhibit the immune response." (PMID 39718433, 2024).
tumor (continued). "To ascertain the relationship between pTCD8+CD28- levels and patients’ tumour immunity, we initially compared the TILs infiltration in individuals with high and low levels of pTCD8+CD28-." (PMID 38519706, 2024). "CD28 signaling enhances the initial conjugation of T cells and APCs (including tumor cells), playing a critical role in cellular adhesion, which is crucial during the early activation stages." (PMID 39684559, 2024). "Blocking CD28 signalling in Tregs impairs their stability and function, inhibits their ability to suppress anti-tumor immune responses, and facilitates tumor surveillance." (PMID 39227959, 2024). "The kinetics of tumor elimination was studied in the NALM/6 ALL model to compare the contribution of the CD28 and 4-1BB domains to therapeutic efficacy." (PMID 38455066, 2024). "CD28 costimulation is thought to enhance metabolic adaptation of tumor-infiltrating lymphocytes to restore metabolism and function in the TME43–45." (PMID 38228846, 2024). "In T cells, conventional CARs based on CD28 are characterized by intense cellular activation, consequently leading to rapid cytolytic capacity and tumor elimination, both of which are significantly higher than those exerted by CAR41BB." (PMID 39364400, 2024). "Repeating the experiment with a different donor T-cell, including mock and 4-1BB variants of the anti-CEA scFab CAR-T cells, also showed similar results with the best tumor inhibition observed in CD28-scFab-CAR-T." (PMID 39759518, 2024). "For generic T cell interaction, splenic T cells from tumor-naïve mice were activated with plate-bound anti-Cd3e/Cd28-antibodies (Tp cells) to serve as controls for tumor-antigen dependent T cell responses." (PMID 38654067, 2024). "The only cytosolic domain of PD-1-CD28 fusion receptor or PD-L1-specific CSR is derived from the costimulatory molecule CD28, and the purpose of expressing these chimeric receptors is to enhance the functionality of tumor-specific TCR-T or CAR-T cells." (PMID 38726005, 2024). "Previous studies have shown that the P28BBz receptor, containing signaling domains of CD28, 4-1BB, and CD3zeta, outperforms receptors with only one or two of these domains in vivo, enhancing T-cell survival, cytokine release, and tumor-killing ability." (PMID 38402232, 2024). "The CD28 stromal LI showed a statistically significant difference in the invasive front (p = 0.002), as well as in the tumor core (p = 0.001), with higher values in cSCC than in BCC cases." (PMID 39329753, 2024). "CAR-T cells with CD28 costimulatory domain were able to achieve faster tumor eradication within the first 7 days when the dose was reduced to levels below the therapeutic dose (4×105, 2×105 and 1×105 CAR-T cells)." (PMID 38455066, 2024). "In particular, the CD28 co-stimulatory pathway has been shown to play a pivotal role in blocking immune checkpoints, thus enhancing anti-tumor responses." (PMID 38752473, 2024). "We found that ARS2 was induced in the tumor microenvironment and tumor-draining lymph nodes by T-cell activation in a CD28 costimulation-dependent manner and was necessary for antigen-specific control of tumor growth in mouse models." (PMID 38233562, 2024). "Antigen-presenting cells display tumor antigens to stimulate tumor-specific T cells via the T cell receptor and co-stimulatory molecules such as CD28." (PMID 38792904, 2024). "We subsequently co-cultured for 36 h the polarized macrophages with sub-optimally activated T cells (CD3/CD28 and IL-2) isolated from spleens of non-tumor-bearing mice." (PMID 38302493, 2024). "Although, CD28 based CAR T-cells elicit a robust acute anti-tumor response, they are more prone to early exhaustion, terminal differentiation and cell death due to their strong signaling patterns." (PMID 39885989, 2024). "The IFN-I gene signature identified in tumor-infiltrating CD4+ T cells was also enriched in in vitro-CD3/CD28-activated CD4+ T cells." (PMID 38383773, 2024).
tumor (continued). "Emphasis was placed on the fact that CD28 co-stimulated MSLN CAR-T cells had a greater killing ability against tumor spheroids expressing heterogeneous MSLN compared to MBBz CAR-T cells." (PMID 38919533, 2024). "This pathway starts from CD28 expressed on tumor plasma cells and, through the PI3K-miR29b-DNMT3B axis, leads to epigenetic silencing of immunoproteasome subunits, allowing MM plasma cells to elude immunosurveillance." (PMID 38654298, 2024). "CD80 promotes T cell activation and anti-tumor immune response by binding to CD28 on the surface of T cells." (PMID 39290697, 2024). "Cbx4 in CD8+ T cells gradually decayed after anti-CD3/CD28 antibody stimulation, similar to the results observed in tumor and splenic T cells." (PMID 38994031, 2024). "According to our data, however, high level of pTCD8+CD28- appears to indicate a positive tumour immunity in HER2 + MBC." (PMID 38519706, 2024). "An adenovirus encoding B7-1 (Ad.mB7-1) and B7-2 (Ad.mB7-2), ligands for T cell receptor CD28, were coupled with adenoviral-IL-2 delivery in PyMT and neu tumors to induce complete tumor regression after a single i.t. injection in a mouse model." (PMID 38803496, 2024). "In the second-generation CARs, the addition of a costimulatory domain with 4-1BB or CD28 enhanced cell persistence and improved anti-tumor responses and increased remission rates in leukemia." (PMID 38785789, 2024). "Amongst these third generation CAR constructs, CD3ζ-CD28-4-1BB seems to be the most promising given the CD28 costimulatory domains contribute to rapid tumor elimination while the 4-1BB endodomains increase CAR survival." (PMID 39835140, 2024). "Meanwhile, the co-stimulatory molecule CD28 can amplify tumor-specific cytotoxic T lymphocytes during the development of KIRC." (PMID 38180750, 2024). "Nevertheless, fortunately there were very small percentage of tumor cells that were carefully observed perforating killing after supplementing with CD28 costimulatory signals." (PMID 39158647, 2024). "In the stimulatory status, CD86 can up-regulate its expression via antigen-presenting cells (APCs), and further combine with CD28 delivering stimulation signals to promote anti-tumor immune and enhance activating T cells." (PMID 39007147, 2024). "The results showed a significant correlation between CHST11 and certain tumor immunostimulators (CD28, IL2RA, and TNFSF13B), tumor immunoinhibitors (CD96 and LGALS9), and MHC proteins (HLA-DRA and HLA-DMB)." (PMID 38565604, 2024). "Our data revealed that CAR5 (CD28 TMD‐FcεRIγ SD) with one ITAM demonstrated the weakest activity against tumour cells." (PMID 38830795, 2024). "The trispecific antibody SAR442257 binds to CD38, CD3, and CD28 to enable both tumor targeting and TC activation." (PMID 38786100, 2024). "CAR-NK-92 cells based on CD28-4-1BB-CD3ζ target Wilms tumor protein with HLA-A2 complex for the elimination of CD3 or CD5 expressing malignant T cells." (PMID 39633491, 2024). "The expression of PD-1, PD-L1, and CD28 was significantly higher in both the tumor core and the invasive front of cSCC samples as compared to BCC (p < 0.001)." (PMID 39329753, 2024). "In this study, we developed a method to generate TITR mimics from peripheral blood mononuclear cell (PBMC)-derived Tregs, employing CD3/CD28 activator, interleukin 2 (IL-2), vitamin D3 (VitD3) and tumor cell-conditioned medium (TCM)." (PMID 38231448, 2024). "It has been shown that CAR-T cells using 4-1BB as costimulatory signal exhibit slower anti-tumor effects compared to CD28, nevertheless they display increased persistence." (PMID 39594822, 2024). "Taking these data together, the CD28 HTM domain imparted a greater tumor-killing activity and better persistence than a CD8 HTM in the second-generation CAR design with a 4-1BB CSD." (PMID 39043633, 2024).